STAT3 (signal transducer and activator of transcription 3)
Diseases named in the same sentence as STAT3 in open-access papers (continued):
Sharing a sentence is not in itself a finding about the gene and the disease.
gastric cancer (continued). "PPI, another important active component extracted from Rhizoma Paridis, has been shown to inhibit STAT3 activation in gastric cancer cells." (PMID 36233191, 2022). "We performed the Western blot assay to investigate the effect of SDL-1 on the STAT3 signaling pathway in gastric cancer cells." (PMID 36034876, 2022). "This study aimed to investigate the mechanism of lncRNA RPSAP52-mediated miR-665/STAT3 signaling pathway in gastric cancer, and to propose new targets for the treatment of gastric cancer." (PMID 35322746, 2022). "In conclusion, our study demonstrates that EVs overexpressing L-PGDS inhibit gastric cancer progress by regulating cancer cell stemness and suppressing STAT3 phosphorylation." (PMID 35087591, 2022). "Mechanism studies have shown that upregulated HEIH binds miR-4500 to affect autophagy and glycolysis through the STAT3 signaling pathway and promote the proliferation and migration of gastric cancer cells." (PMID 36246567, 2022). "CXCL5 derived from TAMs in gastric cancer promotes metastasis by activating the CXCR2/STAT3 feed-forward loop." (PMID 35853880, 2022). "Signal transducer and activator of transcription 3 (STAT3) has been elucidated as a promising target for developing anticancer drugs in gastric cancer." (PMID 36034876, 2022). "Berberine and 5-fluoruracil synergistically inhibited STAT3 and surviving to induce gastric cancer cell death." (PMID 36700235, 2022). "Our previous study demonstrated the anti-metastatic function of piperine by blocking IL-1β-stimulated IL-6 via the downregulation of the p38 and STAT3 activation in gastric cancer TMK-1 cells." (PMID 35326180, 2022). "Another study found that apatinib and cinobufagin encapsulated in a pH-responsive liposome induced pyroptosis and apoptosis in gastric cancer cells via the VEGFR2/STAT3 signaling pathway." (PMID 36038533, 2022). "In this study, we report the design and synthesis of a series of STAT3 PROTACs based on S31-201 against gastric cancer for the first time, providing a possible direction for the clinical treatment of gastric cancer." (PMID 36034876, 2022). "Sekikawa and others found that STAT3 can play a role in inhibiting the apoptosis of gastric cancer cells, and the overactivation of STAT3 is closely related to the progression of gastric cancer." (PMID 35958524, 2022). "IL-8 has been shown to induce PD-L1 expression in gastric cancer cells via c-Myc regulated by STAT3/mTOR signaling activation, resulting in immune escape of tumor cells." (PMID 36185222, 2022). "Our results demonstrated that gastric cancer cell with STAT3 knockout inhibited LAMC1 expression on protein levels significantly and STAT3 didn't affect LAMC1 mRNA expression." (PMID 35541892, 2022). "The reason for the obvious increase in PD-L1 in ERBB2-overexpressing gastric cancer is that STAT3 in the ERBB2 pathway and the ERBB2d16 pathway can directly increase the expression of PD-L1 in tumor tissue, as reported." (PMID 35463314, 2022). "In gastric cancer, IL-26-activated STAT3 inhibits apoptosis by inducing the upregulation of the anti-apoptotic genes Bcl-2 and Bcl-XL and the oncogene c-Myc." (PMID 36038533, 2022). "Totally, palmitic acid/p-STAT3/miR-193a-3p/LAMC1 regulation circuitry was favorable for gastric cancer peritoneal metastasis." (PMID 35541892, 2022). "Our results suggest that HEIH can inhibit autophagy by regulating STAT3 in gastric cancer cell lines." (PMID 36246567, 2022). "We in silico analyzed the essentiality of STAT3 for the growth of gastric cancer cell lines identified by Chronos’ and Achilles’ projects." (PMID 36034876, 2022). "Apigetrin inhibits gastric cancer progression by inducing apoptosis and regulating the ROS-modulated STAT3/JAK2 pathway." (PMID 36445338, 2022). "In this study, we found STAT3 is overexpressed and correlated with poor prognosis of gastric cancer." (PMID 36034876, 2022).
gastric cancer (continued). "In ESCC, the distribution of STAT3 and p-STAT3 is consistent with that of gastric cancer and AEG and promotes the malignant progression of ESCC by increasing the expression of VEGF and CyclinD1." (PMID 36225196, 2022). "We confirmed that miR-21 expression in a preclinical model of early gastric cancer is dependent on Stat3 downstream of the IL-6 family cytokine-mediated activation of gp130 receptor signaling." (PMID 35053428, 2022). "The expression levels of Stat3, PD-1 and PD-L1 differed in gastric cancer and normal tissues adjacent to the cancer in TCGA database." (PMID 36454780, 2022). "Among them, the SDL-1 achieves the degradation of STAT3 protein in vitro, and exhibits good anti-gastric cancer cell proliferation activity, inhibits invasion and metastasis of MKN1 cell, and induces MKN1 cell apoptosis and arrests cell cycle at the same time." (PMID 36034876, 2022). "A previous study demonstrated that the signal transducer and activator of transcription 3 (STAT3) signaling pathway played a key role in the proliferation of gastric cancer mediated by EXOSC5." (PMID 36293016, 2022). "Further mechanistic studies revealed that gastric cancer cells orchestrate palmitic acid/p-STAT3/miR-193a-3p/LAMC1 axis to support more LAMC1 secretion, which further favors preadipocyte maturation to consolidate pre-metastatic niche." (PMID 35541892, 2022). "Our results prove the potential of terphenyllin as a STAT3 inhibitor in the treatment of gastric cancer, which will provide a basis for the further development of this natural compound as a targeted drug." (PMID 35401187, 2022). "For instance, LINC00467 was highly expressed in gastric cancer and drove the malignant progression of gastric cancer through the miR-27b-3p/STAT3 axis." (PMID 35587748, 2022). "The pro-inflammatory cytokines IL-1β, TNF, and IL-6 can induce the transition of EMT in head and neck cancers and anti-inflammatory cytokine IL-10 can lead to tumor cell proliferation through an induction of STAT3 activation in gastric cancer cells." (PMID 35283421, 2022). "The recent manuscript by Wei K.L. and coworkers reported the data obtained through an Illumina 850K methylation microarray in AGS gastric cancer cell lines and in cells depleted of STAT3." (PMID 35627246, 2022). "We corroborated our preclinical findings by correlating high STAT3 and miR-21 expression with the reduced survival probability of gastric cancer patients." (PMID 35053428, 2022). "One study found that MA was able to inhibit IL-6 expression, induce JAK and STAT3 phosphorylation, and down-regulate STAT3-mediated protein Bad, Bcl-2 and Bax expression to treat gastric cancer." (PMID 36557864, 2022). "This is consistent with our findings that Stat3 activity is negatively correlated with regulatory T cells in gastric cancer." (PMID 36454780, 2022). "In our study, p-STAT3/miR-193a-3p/LAMC1 signaling axis is corroborated to have a powerful effect in metastasis of gastric cancer to adipocyte-rich peritoneum which provides a new sight for targeted therapy." (PMID 35541892, 2022). "LINC00152, which was later called STAiR18, was identified in 2013 by analyzing the expression profile of signal transducer and activator of transcription 3 (STAT3)-dependent genes in gastric cancer." (PMID 36033524, 2022). "The results showed that STAT3 was distributed in the nucleus and cytoplasm of gastric cancer, while p-STAT3 was only distributed in the nucleus." (PMID 36225196, 2022). "Among them, IL-6 activates the STAT3 pathway, and IL-1β can reduce gastric acid secretion, ultimately leading to the development of H. pylori gastritis or even gastric cancer." (PMID 36249768, 2022). "Our results showed that almost gastric cancer cell lines exhibited growth modulation related to STAT3 expression." (PMID 36034876, 2022). "Studies have shown that PD-L1 expression in gastric cancer regulates the production of c-Myc to promote tumor development through STAT3/mTOR signaling." (PMID 36439438, 2022).
gastric cancer (continued). "In a mouse model of spontaneously developing gastric cancer by activated STAT3 signaling, chemokines CXCL13, CCL19, and CCL21 were induced simultaneously with tumorigenesis and TLS formation." (PMID 35552285, 2022). "MiRNAs can not only be used as biomarkers of gastric cancer, but also affect Akt and Akt, NF-κB, RAGE, ARF6, TCF4, STAT3 and other signaling pathways promote or inhibit the occurrence and development of gastric cancer." (PMID 35093110, 2022). "To investigate the effect of terphenyllin on the STAT3 signaling pathway, we test the inhibitory effect of terphenyllin on STAT3 protein in gastric cancer cells." (PMID 35401187, 2022). "For example, PVT1 stimulated angiogenesis by triggering the STAT3/VEGFA signaling pathways in gastric cancer." (PMID 35813862, 2022). "Gastric cancer derived mesenchymal cells secrete IL-6 and IL-8 (CXCL8) through JAK2/STAT3 signaling pathway and induce polarization of gastric cancer M2-macrophages." (PMID 35479325, 2022). "CYT997 inhibits the JAK/STAT3 signaling pathway by inducing mitochondrial ROS accumulation, thereby promoting autophagy and apoptosis in gastric cancer cells." (PMID 36038533, 2022). "EVs-L-PGDS inhibited gastric cancer growth, induced cell apoptosis, reduced the expression of stem cell markers including Oct4, Nanog, and Sox2, and inhibited STAT3 phosphorylation in SGC-7901 gastric cancer cells." (PMID 35741334, 2022). "The expression/activation of IL-6, p-Stat3, PD-1 and PD-L1 in gastric cancer (GC) tissues were examined to evaluate their abilities in predicting the survival prognosis in postoperative patients with GC." (PMID 36454780, 2022). "For example, miR‐98 can promote IVDD through the IL‐6/STAT3 signalling pathway, whereas miRNA‐558 promotes gastric cancer progression by attenuating Smad4‐mediated repression of heparinase expression." (PMID 35187741, 2022). "For example, CYT997 inhibits the JAK/STAT3 signaling pathway by inducing mitochondrial ROS accumulation, thereby promoting autophagy and apoptosis in gastric cancer cells." (PMID 36038533, 2022). "RA simultaneously inhibits the expressions of HIF-1α, IL-6, and signal transducers and activators of transcription 3 (STAT3), along with the phosphorylation of STAT3, suggestive of glycolytic inhibition in gastric cancer cells through the IL-6/STAT3 pathway." (PMID 36438836, 2022). "It has been reported that as many as 70% of human tumors have abnormal enhancement of STAT3 activity, including gastric cancer, esophageal cancer, liver cancer, and other tumors." (PMID 35958524, 2022). "By downregulating CD40 and STAT3 expression, miR-502-5p can downregulate PD-L1 expression in gastric cancer (GC) cells." (PMID 35907881, 2022). "Mechanistically, EVs-L-PGDS reduced the expression of stem cell markers including Oct4, Nanog, and Sox2 and inhibited STAT3 phosphorylation in gastric cancer cell SGC-7901." (PMID 35087591, 2022). "Then TCGA gastric cancer survival data were divided into high expression and low expression groups based on the median value of STAT3 expression." (PMID 36034876, 2022). "In conclusion, this study demonstrates that SDL-1 is a potent STAT3 degrader, induces STAT3 protein degradation in vitro, and inhibits gastric cancer growth and metastasis." (PMID 36034876, 2022). "In our present study, we demonstrated that ZIPK activates IL‐6/STAT3 signaling pathway via Ser727 phosphorylation in gastric cancer cells." (PMID 34375503, 2021). "In this study, we further identified a putative STAT3 target, C11orf87, showing differential hypomethylation in gastric cancer cell lines and patient samples with lower STAT3 activation status." (PMID 33886682, 2021). "MBDcap-Seq and expression microarray were performed to identify genes that were epigenetically silenced in AGS gastric cancer cell lines depleted of STAT3." (PMID 33718136, 2021). "Suppression of JAK/STAT3 pathway, for instance, by piperlongumine, results in gastric cancer inhibition." (PMID 33981228, 2021).
gastric cancer (continued). "In the present study, we investigated the relationship between miR-301a-5p and SCIN and their regulatory effects via STAT3 and NF-κB signaling on the proliferation and motility of gastric cancer cell lines." (PMID 34405002, 2021). "The purpose of this study was to identify genes that were epigenetically silenced by STAT3 in gastric cancer." (PMID 33718136, 2021). "In gastric cancer, this effect is related to STAT3 activation, which leads to an increase in Ror1 receptor tyrosine kinase expression." (PMID 33800554, 2021). "TFF1 plays a negative role in regulating H. pylori-mediated activation of NF-κB and STAT3 in gastric cancer cells." (PMID 34419066, 2021). "Luteolin selectively kills gastric cancer cells that are overactivated by STAT3, and these cells are usually drug-resistant." (PMID 34539403, 2021). "In the current study, by methylomic analysis, we identified that miR-193a, a potential STAT3 target, is epigenetically silenced by DNA methylation in gastric cancer cells." (PMID 33718136, 2021). "TMEM119 has been reported by previous study to enhance gastric cancer cell migration and invasion by activating STAT3 signaling pathway." (PMID 33731124, 2021). "Integrative computational analyses identified several putative STAT3 targets showing promoter hypomethylation in STAT3-depleted AGS cells and gastric cancer patients showing lower STAT3 activation (as determined by STAT3 nuclear translocation)." (PMID 33886682, 2021). "Our data suggest that miR-301a-5p acts as an oncogene by suppressing the expression of SCIN and regulating gastric cancer progression via STAT3 and NF-κB signaling." (PMID 34405002, 2021). "Additional experiments led researchers to discover that when SHP-1 protein expression was increased, gastric cancer cells exhibited reduced phosphorylation of STAT3, which resulted in downstream inhibition of Cyclin D1 and XIAP." (PMID 34884670, 2021). "In this study, we investigated H. pylori-mediated activation of STAT3 and NF-κB in gastric cancer, using in vitro and in vivo models." (PMID 34419066, 2021). "NF-κB and STAT3 are two major inflammatory pathways that promote the initiation and progression of several cancers, including gastric cancer." (PMID 34419066, 2021). "ZIPK activates the IL‐6/STAT3 signaling pathway via Ser727 phosphorylation in gastric cancer cells and increases IL‐6‐induced STAT3‐dependent transcription." (PMID 34375503, 2021). "TQ has also been shown in studies to reduce cell proliferation by blocking the activation of the JAK2/STAT3 signaling pathway in gastric cancer cells both in vitro (HGC27, BGC823, and SGC7901 cell lines) and in a xenograft tumor mouse model." (PMID 35010954, 2021). "Effective blockade of STAT3 activity by the STAT3 inhibitor stattic sensitized gastric cancer cells to cisplatin and reduced expression of the cisplatin resistance‐related genes G3BP2, THOC1, ATP7A, and OTUD1." (PMID 34375503, 2021). "Another study demonstrated the ability of CT to potentiate the antitumor effects of doxorubicin on gastric cancer cells through down regulation of STAT3 target genes such as Bcl-xL, Mcl-1, surviving and XIAP." (PMID 33544704, 2021). "Mesenchymal stem cells (MSCs), found in the TME of gastric cancers, express IL-8, which induces PD-L1 expression in gastric cancer cells through STAT3 and mTOR signaling." (PMID 34063096, 2021). "The expressions of SLCO4A1-AS1 and STAT3 were increased, while the expression of miR-149-5p was suppressed in gastric cancer tissues and cell lines." (PMID 34712324, 2021). "STAT3 can accelerate the proliferation of gastric cancer by mediating the upregulation of vascular endothelial growth factor expression." (PMID 34926570, 2021). "Although we demonstrated that SLCO4A1-AS1 positively regulates STAT3 through sponging miR-149-5p in gastric cancer cells, the downstream regulatory mechanism of STAT3 in gastric cancer still needs to be verified." (PMID 34712324, 2021).
gastric cancer (continued). "The IL-6/STAT3 signaling pathway has been investigated in gastric cancer research, and activation of IL6ST enhances carcinogenesis." (PMID 33995063, 2021). "The macrophages differentiated by gastric cancer-derived EVs promoted the migration ability of gastric cancer cells, and the EVs carried STAT3 protein." (PMID 33509150, 2021). "This discovery was consistent with the finding that PD-L1 is upregulated after treatment with CXCL11, accompanied by activation of STAT3 and Akt in gastric cancer." (PMID 33777950, 2021). "Inhibition of the STAT3 pathway remarkably restores the sensitivity of gastric cancer cells to chemotherapeutic agents and increases apoptosis in drug‐resistant cells." (PMID 34375503, 2021). "Previous studies demonstrated that activation of STAT3 is crucial for the development and progression of gastric cancer." (PMID 33886682, 2021). "For instance, TAM-derived IL-10 promotes proliferation and invasion in gastric cancer by activating the c-Met/STAT3 signaling pathway." (PMID 33406733, 2021). "CXCR2 ligands, produced by TAM, significantly promote proliferation and migration of gastric cancer cells through activating a CXCR2/STAT3 feed-forward loop." (PMID 34012923, 2021). "Constitutive activation of STAT3 and overexpression of its target gene Bcl‐2 and c‐Myc are detected in cisplatin‐resistant gastric cancer cells." (PMID 34375503, 2021). "PVT1 directly interacts with p-STAT3 to activate the STAT3 signaling pathway, thereby promoting angiogenesis in gastric cancer." (PMID 34922601, 2021). "A previous study indicated that PVT1 was linked to the activation of STAT3/VEGFA signaling and promoted angiogenesis in patients with gastric cancer." (PMID 34336125, 2021). "Our previous data also demonstrated that CMTM3 suppressed the metastasis of gastric cancer through the EGFR/STAT3/EMT signaling pathway by interacting with Rab5." (PMID 34560882, 2021). "BBR has been shown to suppress growth and cause apoptosis in gastric cancer cell lines owing to the inhibition of EGFR signaling, which includes STAT3 phosphorylation." (PMID 34885950, 2021). "Effective blockade of the STAT3 activity by STAT3 inhibitor sensitized gastric cancer cells to cisplatin and reduced the cisplatin‐resistant‐related gene G3BP2, THOC1, ATP7A, and OTUD1 expression." (PMID 34375503, 2021). "On the other hand, in gastric cancer, migration is associated with CXCL16 activation of STAT3, which leads to an increase in Ror1 receptor tyrosine kinase expression." (PMID 33800554, 2021). "SIRT6 overexpression also induced apoptosis of gastric cancer cells via regulating JAK2/STAT3 signaling." (PMID 34927546, 2021). "Although C11orf87 methylation is independent of its expression, ectopic expression of a constitutive activated STAT3 mutant upregulated its expression in gastric cancer cell line." (PMID 33886682, 2021). "Recently, a study demonstrated that SIRT1, a histone deacetylase that participated in STAT3 deacetylation, was found to be upregulated in advanced gastric cancer." (PMID 33886682, 2021). "SHP-1, a non-receptor, tyrosine-specific PTP that exhibits tumor suppressor activity in gastric cancer, was found to dephosphorylate and inhibit STAT3 signaling in vitro and in vivo." (PMID 34884670, 2021). "We have previously compared the methylation profile between constitutive STAT3-activated AGS gastric cancer cells, and the subline depleted of STAT3 using Illumina 850K methylation microarray." (PMID 33886682, 2021). "Stattic strongly reduced STAT3 phosphorylation and the mRNA levels of IL‐6 in gastric cancer cells with high ZIPK expression." (PMID 34375503, 2021). "Taken together, our results demonstrated that miR-193a was silenced by STAT3-mediated epigenetic mechanism in gastric cancer cells." (PMID 33718136, 2021). "Previous studies also confirmed that STAT3 activation is decisive for the initiation, and progression in gastric cancer patients." (PMID 33886682, 2021).